MYO5A (myosin VA)
Description:
Processive actin-based motor that can move in large steps approximating the 36-nm pseudo-repeat of the actin filament. Can hydrolyze ATP in the presence of actin, which is essential for its function as a motor protein. Involved in melanosome transport. Also mediates the transport of vesicles to the plasma membrane (By similarity). May also be required for some polarization process involved in dendrite formation (By similarity).
Synonyms: MYH12; MYO5; GS1; MYR12
Tractability: Small molecule: a structure with a bound ligand is known. PROTAC: ubiquitination databases record sites on it; its protein half-life has been measured.
Gene: Protein-coding gene on chromosome 15 (52,307,281 to 52,529,132, reverse strand). Ensembl gene ENSG00000197535.
Subcellular location (Human Protein Atlas): Centriolar satellite; Focal adhesion sites; Basal body; Calyx; Cytosol; Primary cilium
Pathways (Reactome):
Developmental Biology: Regulation of MITF-M-dependent genes involved in pigmentation
Disease: FCGR3A-mediated phagocytosis
Immune System: Regulation of actin dynamics for phagocytic cup formation
Metabolism of proteins: Insulin processing
Vesicle-mediated transport: Translocation of SLC2A4 (GLUT4) to the plasma membrane
Gene Ontology:
Molecular function: ATP hydrolysis activity; protein binding; RNA binding; small GTPase binding; actin filament binding; microfilament motor activity; ATP binding; catalytic activity; cytoskeletal motor activity
Biological process: post-Golgi vesicle-mediated transport; regulation of Golgi organization; vesicle transport along actin filament; actin filament-based movement; cellular response to insulin stimulus; endocytosis; melanosome transport; protein localization to plasma membrane; vesicle-mediated transport; establishment of vesicle localization
Cellular component: actin filament; cytoplasm; cytosol; early endosome; endoplasmic reticulum; extracellular exosome; filopodium tip; late endosome; lysosome; melanosome; membrane; peroxisome; recycling endosome; ruffle; vesicle; actin cytoskeleton; growth cone; insulin-responsive compartment; neuron projection; cytoplasmic vesicle; myosin complex
Genetic constraint (gnomAD): Loss-of-function variants: 82 observed, 213.65 expected, observed/expected ratio (o/e) 0.38, 90% interval 0.32 to 0.46. The upper end of that interval is the gene's LOEUF score, 0.46, which puts it in group 2 of 6, group 1 being the genes least tolerant of losing a copy. Missense variants: 1,537 observed, 2,198.5 expected, observed/expected ratio (o/e) 0.7, 90% interval 0.67 to 0.73. Synonymous variants: 719 observed, 790.93 expected, observed/expected ratio (o/e) 0.91, 90% interval 0.85 to 0.97.
Gene-disease validity (ClinGen):
ClinGen rates the evidence that MYO5A causes each of these diseases.
Griscelli syndrome type 1 (autosomal recessive): Definitive.
Homologues: Orthologues: chimpanzee MYO5A (99% identical), macaque MYO5A (99% identical), dog MYO5A (98% identical), rabbit MYO5A (98% identical), rat Myo5a (97% identical), pig MYO5A (96% identical), mouse Myo5a (96% identical), guinea pig MYO5A (95% identical), tropical clawed frog myo5a (86% identical), zebrafish myo5aa (78% identical). Paralogues in human: MYO5B (62% identical), MYO5C (51% identical), MYH2 (27% identical), MYH3 (27% identical), MYH7 (27% identical), MYH6 (27% identical), MYH1 (27% identical), MYH4 (27% identical), MYH8 (27% identical), MYH10 (26% identical), MYH7B (26% identical), MYH9 (26% identical), and 32 more.
Diseases named in the same sentence as MYO5A in open-access papers:
MYO5A is named in the same sentence as 79 diseases in open-access papers, as found by Europe PMC text mining. Sharing a sentence is not in itself a finding about the gene and the disease. The quoted sentences say what the papers report.
Griscelli syndrome (16 papers, 2012 to 2025). Griscelli syndrome (GS) is characterized by silvery gray sheen of the hair and hypopigmentation of the skin which can be associated to neurological impairment (type 1), immunodeficiency (type 2) or be isolated (type 3). "In agreement with the role of MYO5A outside the cilium, mutations in MYO5A cause Griscelli syndrome, characterized by hypopigmentation, neurological impairment, and hypotonia, characteristics distinct from other ciliopathies." (PMID 39882846, 2025). "The absence of ciliation defects in MYO5A knockout cells differs from the previous observation, but is consistent with the fact that mutations in MYO5A gene cause Griscelli syndrome, of which phenotypes are distinct from ciliopathies." (PMID 39882846, 2025). "Autosomal recessive loss of function of MYO5A and subsequent pigment dilution is characteristic of Griscelli syndrome." (PMID 38390852, 2024). "MYO5A encodes myosin 5A, and mutations in this gene are associated with Griscelli syndrome, which is characterized by hypopigmentation and a primary neurological abnormality." (PMID 36539902, 2022). "No pathogenic variants were identified in genes associated with Chediak-Higashi syndrome (LYST) or Griscelli syndrome (MYO5A, RAB27A, MLPH) in the 6 patients who underwent whole exome sequencing analysis." (PMID 30791930, 2019). "In family 037 with hindbrain malformation, we identified a homozygous variant in MYO5A, which is responsible for Griscelli syndrome (MIM#214450)." (PMID 27435318, 2016). "A genetic disease called Griscelli syndrome (GS) type I has been linked to mutations in the myo5a gene." (PMID 24339992, 2013). "In human, mutations within any of the genes RAB27A (RAB27A, member RAS oncogene family), MLPH (melanophilin), and MYO5A (myosin VA) encoding for the proteins of the tripartite complex can cause Griscelli syndromes." (PMID 24376820, 2013). "Similarly, mutations in the MYO5A gene, that encodes the cargo-transporting MYO5A, have been associated with Griscelli’s Syndrome, a debilitating neurological disorder." (PMID 33718386, 2021). "Defects in any of these three genes, melanophilin (MLPH), myosin Va (MYO5A), and Rab27a (RAB27A), have been linked with several dilute phenotypes and the autosomal recessive Griscelli syndromes in humans (OMIM #214450, 607624, 609227)." (PMID 32512769, 2020). "Mutations in the MYO5A (MIM*160777) encoding MYO5A and MLPH (MIM*606526) encoding MLPH/SLAC2-A cause other types of Griscelli syndrome GS-1 (MIM#214450) and GS-3 (MIM#609227), respectively." (PMID 33362801, 2020). "Griscelli syndrome (MIM#214450), characterized by hypopigmentation, is a melanosome transport disorder associated with variants in MYO5A, RAB27A, or MLPH." (PMID 30791930, 2019). "In-depth analysis of three mutants, Krt76, Myo5a (a model of human Griscelli syndrome) and Mysm1, provides validation of the screen." (PMID 24721909, 2014). "Mutations in genes encoding melanosome transport-related molecules, such as MYO5A, RAB27A and SLAC-2A, have been reported to cause a human pigmentary disease known as Griscelli syndrome, which is associated with diluted skin and hair color." (PMID 22844437, 2012). "On the other hand, mutations in the genes encoding MYO5A, RAB27A and MLPH are known to result in one of three subtypes of an autosomal recessive inherited human pigmentary diseases called Griscelli Syndrome (GS), which is mostly characterized as diluted pigmentation in skin and hair." (PMID 22844437, 2012). "Furthermore, one patient with Griscelli syndrome (No. 3) had disease-causing variants in MYO5A gene." (PMID 34540776, 2021). "While Myo5a phenocopied human Griscelli syndrome, a role for Myo7a in epidermal pigmentation was not predicted." (PMID 24721909, 2014).
diabetes (9 papers, 2009 to 2019). "In contrast to the vehicle treated rats, induction of diabetes by STZ resulted in nearly complete loss of myosin Va within the nerve terminals of the neuronal processes ramifying on the muscularis externa." (PMID 25705628, 2014). "Based on preliminary evidence that local intravaricosity transport of nNOSα by myosin Va motor protein is important for efficient NO synthesis during neurotransmission, we hypothesized that deficiency of myosin Va may contribute to impaired nitrergic neurotransmission in diabetes." (PMID 25705628, 2014). "A recent study has demonstrated that in diabetes mellitus, nNOS synthesis and distribution remain relatively unaffected, whereas myosin Va genomic expression is severely impaired, with virtual absence in the nerve terminals." (PMID 26942180, 2016). "A wide range of fields have been shown to demonstrate that an entire spectrum of changes has occurred in myosin Va expression within the neuronal soma after diabetes induction." (PMID 25705628, 2014). "Recently, expression of myosin Va has been reported to be reduced in neuronal tissues from the brain of animal models of diabetes mellitus." (PMID 24516539, 2014). "Specifically, alteration in nNOSα contents within jejunal nerve terminals and a local subcortical transporter myosin Va was tested 16 weeks after induction of diabetes by low dose streptozotocin (STZ) in male Wistar rats." (PMID 25705628, 2014). "It is possible that the transcription factor or factors that drive myosin Va genomic synthesis are exquisitely sensitive to the pathophysiological alterations resulting from STZ-induced diabetes." (PMID 25705628, 2014). "Recent observation has been made regarding significant reduction of myosin Va in myenteric neuronal soma and nerve varicosities of jejunum in streptozotocin-induced diabetes, likely a result of inhibition of genomic transcription of myosin Va." (PMID 25705631, 2014). "In diabetes, it may potentially result from myosin Va defect, or even from a primary myosin heavy chain defect." (PMID 26942180, 2016). "Whether subtle changes in nAChR due to myosin Va genotoxicity are contributory to fatigue in diabetes is a tempting hypothesis." (PMID 26284245, 2015). "It is possible that transcriptional inhibition of myosin Va is a fundamental early-stage molecular pathophysiology operant in all tissues in diabetes, which likely contributes to the observed misalignment of membrane nNOS in skeletal muscles in the diabesity model." (PMID 26284245, 2015). "Our observations of increased perikaryal volumes of some myosin Va neurons in diabetes may have resulted from attenuation of axonal transport." (PMID 25705628, 2014). "Myosin Va expression in myenteric ganglia is much reduced in diabetic tissues in comparison to nNOSα and it seems likely that this selective reduction has taken place early on after diabetes induction." (PMID 25705628, 2014). "In spite of the recent studies that have shown relationship between diabetes and the expression of molecular motors, as myosin-IIB, myosin heavy-chain, myosin-Va, and myosin-IXB, the pathways linked among myosin expression, oxidative stress, and diabetes mellitus are still unclear." (PMID 24982856, 2013). "Thus, the increase of myosin Va at an early stage of diabetes might be interpreted as an attempt to cope with the diabetes-mediated impairment of axonal transport." (PMID 29351809, 2018). "Specifically, we showed that short-term diabetes alters both the mRNA levels and axoplasm content of KIF1A and KIF5B and axoplasm content of KIF5A and Myosin Va, but only in male animals." (PMID 29351809, 2018). "We recently demonstrated that acute diabetes (20 days) alters protein and mRNA expression of myosin-IIB and myosin-Va in the rat brains." (PMID 24982856, 2013).
diabetes (continued). "Previous studies showed a decrease in myosin Va in brain neuronal cell bodies of STZ-rats at an early stage of diabetes, as well as in jejunal musculomotor nerve terminals 16 weeks after induction of diabetes." (PMID 29351809, 2018). "Thus, there is a potential for pharmacological reversal of myosin Va transcriptional inhibition, at least in the early phases after STZ induction of diabetes." (PMID 25705628, 2014). "This indicates that the axonal transport of nNOSα is likely not impeded in diabetes, unlike myosin Va axonal transport, which is severely impaired." (PMID 25705628, 2014). "The intact axonal transport of nNOSα in diabetes is sharply contrasted against the nearly absent axonal transport of myosin Va in diabetes at the specific time point examined." (PMID 25705628, 2014). "Diabetes also induced an alteration in Myosin Va in males but not in females." (PMID 29351809, 2018). "In summary, the results of the present study show the dissociation between presences of the key inhibitory neurotransmitter synthesizing enzyme nNOSα in the nerve terminals but absence of its local transporter myosin Va in the jejunum of rats after 16 weeks of diabetes induction with STZ." (PMID 25705628, 2014). "We show that short-term diabetes alters mRNA levels and axoplasm protein contents of kinesin family member KIF1A, KIF5B, KIF5A and Myosin Va in male but not in female rats." (PMID 29351809, 2018).
melanoma (8 papers, 2010 to 2023). A malignant, usually aggressive tumor composed of atypical, neoplastic melanocytes. "Myosin Va was demonstrated to associate with the ER in mouse melanoma cells and transport ER vesicles in squid axons." (PMID 20856877, 2010). "MLPH, Rab27a, and Myo5a form ternary complexes, which play a key role in the transfer of melanoma bodies from melanocytes to neighboring keratinocytes and ultimately color the animal coat." (PMID 33466315, 2021). "MYO5A plays an important role in malignant melanoma, and its expression was found to be elevated in a number of highly metastatic cancer cell lines and metastatic colorectal cancer tissues." (PMID 32735728, 2020). "As research progressed, MYO5A was also found to perform a critical effect in malignant melanoma." (PMID 37667251, 2023). "MYO5A also promotes anchorage-independent growth, invasion and migration in melanoma." (PMID 34072264, 2021). "Among them, 6 genes (NPTX1, AUTS2, RPS6KA2, KAT2B, MYO5A and HMG20B) were simultaneously downregulated in the melanoma samples compared with the noncancerous samples in GSE31909 and GSE35388 microarray data." (PMID 37384727, 2023).
Griscelli syndrome type 1 (7 papers, 2013 to 2021). A Griscelli syndrome characterized by silvery gray sheen of the hair, hypopigmentation of the skin and neurological impairment without immunodeficiency that has material basis in mutations in the MYO5A gene on chromosome 15q21.2. "MYO5A loss of function variants cause Griscelli type 1 syndrome in humans, lavender foal in horses and the phenotype of the dilute mouse mutant." (PMID 34680875, 2021). "Mutation of the Myo5a gene causes Griscelli syndrome type 1 in humans and the dilute phenotype in mice, which are both characterised by pigment dilution and neurological defects as a result of impaired vesicle transport in melanocytes and neuroendocrine cells." (PMID 23349704, 2013). "Mutations in the Myo5a gene lead to Griscelli syndrome type 1 in humans, a rare inherited autosomal recessive disorder characterised by hypopigmentation and neurological impairment." (PMID 23349704, 2013). "Griscelli syndrome type 1 (GS1) is caused by mutations of MYO5A and hypomelanosis is accompanied by neurologic deficits, while Griscelli syndrome type 2 (GS2) is caused by RAB27A mutations and patients show immune impairment in combination with the hair color dilution." (PMID 24376820, 2013). "Griscelli syndrome type 1 (GS1), an autosomal recessive disorder, results from mutations in MYO5A gene on chromosome 15q21, which plays a role in melanosome transport and membrane trafficking processes." (PMID 34843009, 2021). "To investigate a possible correlation between depletion of MyoVa protein and SMS transcription, we also evaluated the expression of SMS in MYO5A-null primary fibroblasts isolated from patients with Griscelli Syndrome Type 1/Elejalde syndrome." (PMID 30733278, 2019). "Griscelli syndrome type 1 (GS1) features primary neurological disease and pigment anomalies and it is caused by mutations in the MYO5A gene encoding the motor protein myosin-Va." (PMID 24134793, 2013). "Griscelli syndrome type 3 (GS3) is caused by mutations within MLPH or MYO5A and only MLPH defects are usually not accompanied by severe clinical diseases." (PMID 24376820, 2013).
albinism (4 papers, 2013 to 2026). A congenital disorder characterized by partial or complete absence of melanin pigment in the eyes, hair, or skin. "These variations are caused by mutations in three genes located on the 15q21 region, i.e., MYO5A, RAB27A, and MLPH, giving rise to three distinct clinical forms, respectively, GS1, GS2, and GS3, with albinism as a common feature." (PMID 38993473, 2024). "GS1 exhibits partial albinism and neurological issues without immune effects due to MYO5A mutations." (PMID 41496009, 2026). "Due to impaired Myo5a-dependent melanosome transport these patients exhibit partial albinism." (PMID 24339992, 2013).
Chediak-Higashi syndrome (4 papers, 2017 to 2021). ChC)diak-Higashi syndrome (CHS) is a rare severe genetic disorder generally characterized by partial oculocutaneous albinism (OCA), severe immunodeficiency, mild bleeding, neurological dysfunction and lymphoproliferative disorder. "In addition, NGS did not reveal pathogenic/likely pathogenic variants in the genes associated with Griscelli syndrome type 1-3 (MYO5A, RAB27A, MLPH) or Chediak–Higashi syndrome (LYST)." (PMID 34685610, 2021).
colon cancer (4 papers, 2021 to 2022). "We furthermore identified upregulation of the direct EZH2 target genes CNN3 and AKAP13, that are involved in chemotherapy resistance in colon cancer and breast cancer, respectively, and the genes MYO5A, AKT3 and SPECC1, which are implicated in the evasion of apoptosis." (PMID 33712646, 2021). "For instance, Snail upregulates the expression of an actin‐dependent motor protein myosin Va involved in cell migration and metastasis of cancer, by binding to an E‐box1 at position −825 to −820 of the MYO5A promoter in HT‐29 human colon cancer cells." (PMID 34826187, 2022). "The first study linking these unconventional myosins to colon cancer reported increased MYO5A expression in colon cancer, characterized by lymph nodes or distant metastasis (CRC stages III and IV) in contrast to non-metastatic CRC." (PMID 33670106, 2021). "Functional studies demonstrated that MYO5A depletion impairs migration of different colon cancer cells in vitro and attenuates metastatic spread of these cells in a chicken chorioallantoic membrane assay in vivo." (PMID 33670106, 2021). "Since MyoVin-1 and PBP are likely to inhibit all members of the class V myosins and the reported opposite roles on MYO5A and MYO5B in CRC, the prospects for therapeutic use of class V myosin inhibitors in treating colon cancer remain unclear." (PMID 33670106, 2021).
esophageal squamous cell carcinoma (4 papers, 2021 to 2025). Esophageal squamous cell carcinoma (ESCC) is a type of esophageal carcinoma (EC) that can affect any part of the esophagus, but is usually located in the upper or middle third. "Studies have implicated MYO5A in laryngeal squamous cell carcinoma and esophageal squamous cell carcinoma." (PMID 35957868, 2022). "Increased expression of MYO5A has been observed in several metastatic cell lines, including metastatic colorectal, lung, breast, and prostate cancers, as well as in invasive and metastatic esophageal squamous cell carcinomas." (PMID 41206839, 2025). "Up-regulated expression of LINC01980 in esophageal squamous cell carcinoma confers poor prognosis and as well promotes epithelial-mesenchymal transition (EMT) via the miR-190a-5p and MYO5A pathways." (PMID 33767582, 2021).
breast carcinoma (3 papers, 2021 to 2023). "Knockdown of LncRNA PART1 led to downregulation of cancer-promoting factor MYO5A and suppression of breast cancer metastasis." (PMID 37667251, 2023).